ENSG00000285880 (ADRB3-GOT1L1 readthrough)
Gene: Protein-coding gene on chromosome 8 (37,934,340 to 37,965,953, reverse strand). Ensembl gene ENSG00000285880.
Genetic constraint (gnomAD): Loss-of-function variants: 23 observed, 12.63 expected, observed/expected ratio (o/e) 1.82, 90% interval 1.25 to 1.97. The synonymous counts are far from expectation, so gnomAD's model fits this gene poorly and the ratio says little. Missense variants: 431 observed, 350.11 expected, observed/expected ratio (o/e) 1.23, 90% interval 1.14 to 1.33. Synonymous variants: 203 observed, 146.33 expected, observed/expected ratio (o/e) 1.39, 90% interval 1.24 to 1.56.